SRSF8 (serine and arginine rich splicing factor 8)
Description:
Involved in pre-mRNA alternative splicing.
Synonyms: SFRS2B; SRP46; DSM-1
Tractability: PROTAC: ubiquitination databases record sites on it.
Gene: Protein-coding gene on chromosome 11 (95,066,919 to 95,071,225, forward strand). Ensembl gene ENSG00000263465.
Subcellular location: Nucleus
Subcellular location (Human Protein Atlas): Nucleoplasm; Cytosol
Pathways (Reactome):
Metabolism of RNA: Processing of Capped Intron-Containing Pre-mRNA; mRNA Polyadenylation; mRNA Splicing - Major Pathway
Gene Ontology:
Molecular function: protein binding; RNA binding; nucleic acid binding
Biological process: regulation of alternative mRNA splicing, via spliceosome
Cellular component: nucleoplasm; nucleus
Genetic constraint (gnomAD): Loss-of-function variants: 8 observed, 7.32 expected, observed/expected ratio (o/e) 1.09, 90% interval 0.63 to 1.8. That is too few expected variants to judge how well the gene tolerates losing a copy. Missense variants: 408 observed, 375.97 expected, observed/expected ratio (o/e) 1.09, 90% interval 1 to 1.18. Synonymous variants: 162 observed, 159.13 expected, observed/expected ratio (o/e) 1.02, 90% interval 0.89 to 1.16.
Homologues: Orthologues: chimpanzee SRSF8 (99% identical), macaque SRSF8 (96% identical), tropical clawed frog srsf2 (55% identical), zebrafish srsf2a (54% identical), zebrafish srsf2b (52% identical), Drosophila melanogaster SC35 (37% identical), Caenorhabditis elegans rsp-4 (35% identical). Paralogues in human: SRSF2 (58% identical), SRSF10 (32% identical), SRSF12 (29% identical).
Diseases named in the same sentence as SRSF8 in open-access papers:
SRSF8 is named in the same sentence as 5 diseases in open-access papers, as found by Europe PMC text mining. Sharing a sentence is not in itself a finding about the gene and the disease. The quoted sentences say what the papers report.
osteosarcoma (1 paper, 2024). A usually aggressive malignant bone-forming mesenchymal neoplasm, predominantly affecting adolescents and young adults. "We identified 6 splicing factor genes associated with the prognosis of osteosarcoma patients, namely SRSF1, SRSF4, SRSF5, SRSF7, SRSF8, and SRSF10." (PMID 39286028, 2024).
ovarian insufficiency (1 paper, 2020). "Interestingly, a set of 5 proteins (KHDC3L, SRSF8, PNO1, RASIP1, and MORC2) exhibited a significant association with ovarian insufficiency in this cohort." (PMID 32410729, 2020).
tumor (1 paper, 2023). "In contrast, overexpression of SRSFs (SRSF5 and SRSF8) might enhance the sensitivity of tumor to Src/ABL, mTOR1, and protein phosphatase inhibitors." (PMID 38015716, 2023).
SRSF8 also shares sentences with these, for which no sentence is quoted: Dravet syndrome (1 paper); epilepsy (1).